TM6SF2 (transmembrane 6 superfamily member 2)
Description:
Regulator of liver fat metabolism influencing triglyceride secretion and hepatic lipid droplet content. May function as sterol isomerase.
Synonyms: Lpr4
Tractability: Antibody: UniProt predicts a signal peptide or a membrane-spanning region.
Gene: Protein-coding gene on chromosome 19 (19,264,109 to 19,273,391, reverse strand). Ensembl gene ENSG00000213996.
Subcellular location: Endoplasmic reticulum membrane; Endoplasmic reticulum-Golgi intermediate compartment membrane
Gene Ontology:
Molecular function: identical protein binding; protein binding
Biological process: regulation of lipid metabolic process; lipid homeostasis
Cellular component: endoplasmic reticulum membrane; endoplasmic reticulum-Golgi intermediate compartment membrane
Genetic constraint (gnomAD): Loss-of-function variants: 29 observed, 41.07 expected, observed/expected ratio (o/e) 0.71, 90% interval 0.52 to 0.96. The upper end of that interval is the gene's LOEUF score, 0.96, which puts it in group 4 of 6, group 1 being the genes least tolerant of losing a copy. Missense variants: 475 observed, 487 expected, observed/expected ratio (o/e) 0.98, 90% interval 0.9 to 1.05. Synonymous variants: 200 observed, 201.64 expected, observed/expected ratio (o/e) 0.99, 90% interval 0.88 to 1.12.
Homologues: Orthologues: chimpanzee TM6SF2 (99% identical), macaque TM6SF2 (97% identical), dog TM6SF2 (83% identical), guinea pig TM6SF2 (81% identical), mouse Tm6sf2 (79% identical), rat Tm6sf2 (73% identical), pig TM6SF2 (71% identical), tropical clawed frog tm6sf2 (56% identical). Paralogues in human: TM6SF1 (49% identical).
Diseases named in the same sentence as TM6SF2 in open-access papers:
TM6SF2 is named in the same sentence as 60 diseases in open-access papers, as found by Europe PMC text mining. Sharing a sentence is not in itself a finding about the gene and the disease. The quoted sentences say what the papers report.
Hepatic steatosis (68 papers, 2015 to 2026). Steatosis is a term used to denote lipid accumulation within hepatocytes. "Substitution of lysine for glutamic acid at residue 167 in transmembrane 6 superfamily member 2 (TM6SF2), located on chromosome 19, is associated with fatty liver disease." (PMID 38331795, 2024). "It is interesting to note that mutations in PNPLA3, MBOAT7, and TM6SF2 are associated with fatty liver disease; however, TM6SF2 has a contrasting effect on CKD compared to mutations in PNPLA3 and MBOAT7." (PMID 38247511, 2024). "TM6SF2 has a protective effect on cardiovascular system, but it participates in hepatic steatosis and increases the susceptibility to NASH and hepatic fibrosis." (PMID 36973654, 2023). "The nonsynonymous variant in TM6SF2 (E167K, rs58542926) results in protein dysfunction, leading to an excessive buildup of TG in the liver, thereby contributing to the onset of fatty liver disease." (PMID 37674196, 2023). "TM6SF2 p.E167K was associated in both cohorts with hepatic steatosis, but a biopsy-based analysis of liver fibrosis in the German cohort did not yield a significant association between this variant and liver scarring." (PMID 36555467, 2022). "Liver-specific Tm6sf2-deficient mice spontaneously exhibit hepatic steatosis, fibrosis, and accelerated development of hepatocellular cancer." (PMID 36139452, 2022). "PNPLA3 p.I148M and TM6SF2 p.E167K variants have been also associated to a higher risk of developing hepatic steatosis and advanced fibrosis." (PMID 35625751, 2022). "A polymorphism (rs58542926 A > G) in the transmembrane 6 superfamily member 2 (TM6SF2) gene is associated with hepatic steatosis and progressive fibrosis." (PMID 33544287, 2021). "Tm6sf2 KO mice develop hepatic steatosis, caused by VLDL retention and they reduced circulating cholesterol." (PMID 34680476, 2021). "The single nucleotide polymorphism rs58542926 C>T in transmembrane 6 superfamily member 2 (TM6SF2) is another genetic variant associated to an increased risk to develop hepatic steatosis and fibrosis in children." (PMID 33889132, 2021). "PNPLA3 rs738409 and TM6SF2 rs58542926 are two well-studied SNPs where the minor alleles are reported to be associated with the development of HCC in fatty liver attributed to NAFLD or ARLD." (PMID 33808740, 2021). "The mechanism by which E167K or the loss of TM6SF2 function causes hepatic steatosis, steatohepatitis, and fibrosis is less understood." (PMID 34575933, 2021). "SLC30A10 and SLC39A8 encode metal ion transporters and PNPLA3 and TM6SF2 are known genes associated with fatty liver and cirrhosis." (PMID 32247823, 2020). "We also measured REs in another strain of mice that has fatty liver due to deficiency of TM6SF2, a protein required for lipidation of very low density lipoproteins." (PMID 29555681, 2018). "We analyzed PNPLA3 rs738409 (C/G), MTP493 rs1800591 (G/T), and TM6SF2 rs58542926 (C/T), which are known to be associated with liver steatosis/nonalcoholic steatohepatitis and/or lipid metabolism." (PMID 30576386, 2018). "More recently, a single-nucleotide polymorphism encoding the E167K variant of the transmembrane six superfamily member 2 gene (TM6SF2) was determined to be independently associated with liver steatosis and necroinflammation in chronic hepatitis C patients." (PMID 29258449, 2017). "Chronic inactivation of Tm6sf2 in mice is associated with hepatic steatosis, hypocholesterolemia, and transaminitis, thus recapitulating the phenotype observed in humans." (PMID 27013658, 2016). "To date, the PNPLA3 I148M and TM6SF2 E167K gene variants are the major determinants of interindividual differences in liver steatosis and susceptibility to progressive NASH." (PMID 26273621, 2015). "Although the evidence for an association between the TM6SF2 gene and hepatic steatosis is robust, the disease promoting effect regarding long‐term development of liver cirrhosis or HCC remains unclear." (PMID 36166317, 2022).
Hepatic steatosis (continued). "PNPLA3 p.I148M and TM6SF2 p.E167K were associated with increased hepatic steatosis in our cohort." (PMID 36555467, 2022). "In addition, PNPLA3 and TM6SF2 variants have been regarded as variants of interest for risk of liver steatosis even in transplant settings." (PMID 36028802, 2022). "While PNPLA3 and TM6SF2 appear to be the most prominent population-wide determinants of hepatic steatosis, other relatively rare or less prominent genetic defects in intrahepatic lipid metabolism have been shown to cause fatty liver." (PMID 30355853, 2018). "A missense mutation (E167K) in TM6SF2 (transmembrane 6 superfamily member 2), a polytopic protein of unknown function, is associated with the full spectrum of fatty liver disease." (PMID 27013658, 2016). "For example, a mutated variant of transmembrane 6 superfamily member 2 gene (TM6SF2) which impairs VLDL production, enhances hepatic steatosis and fibrosis." (PMID 40141037, 2025). "Another variant, rs58542926, in the transmembrane 6 superfamily member 2 (TM6SF2) gene, is linked to lower plasma VLDL levels, hepatic steatosis, and higher ALT levels." (PMID 39617908, 2024). "Besides, studies have shown that remnant cholesterol may play a key role in the development of NAFLD/NASH,66, 67 while TM6SF2 may play an inhibitory role in this process, and TM6SF2 deficiency promoted the development of hepatic steatosis, hepatic fibrosis and liver cancer." (PMID 38506086, 2024). "Genetic Biomarkers: Genetic variants associated with hepatic steatosis, such as PNPLA3 and TM6SF2 polymorphisms, have been studied as predictors of disease progression." (PMID 38668326, 2024). "Some genetic variants, for example missense variants in transmembrane 6 superfamily member 2 (TM6SF2) and in patatin phospholipase‐like domain containing protein 3 (PNPLA3) are associated with lipid imbalance resulting in inducing hepatic steatosis." (PMID 38494851, 2024). "The variant in the “transmembrane 6 superfamily member 2” (TM6SF2) gene on chromosome 19 appears to be associated with an impaired lipid transporter and fatty liver disease." (PMID 38891828, 2024). "Polymorphisms in genes such as PNPLA3, TM6SF2, and GCKR promote steatosis through interaction with distinct metabolic mechanisms, predisposing to metabolic dysfunction-associated fatty liver disease." (PMID 38626012, 2024). "The authors found that TM6SF2 acts in the smooth endoplasmic reticulum to promote bulk lipidation of apolipoprotein B-containing lipoproteins, thus preventing fatty liver disease in a study comparing Tm6sf2-/- mice with their wild-type littermates." (PMID 38331795, 2024). "It was found that a variety of gene sites are related to the risk, disease severity, hepatic steatosis and advanced fibrosis of NAFLD, including PNPLA3, TM6SF2, GCKR, MBOAT7, APOC3, HSD17B13, etc.." (PMID 36973654, 2023). "Studies have shown that liver specific TM6SF2 loss impairs VLDL secretion, promotes hepatic steatosis and fibrosis, and accelerates HCC development." (PMID 37753315, 2023). "Consistent with human genetic findings, liver-specific Tm6sf2-deficient mice show significantly reduced TC and TG levels and VLDL particle size while exhibiting spontaneous hepatic steatosis, fibrosis, and accelerated development of hepatocellular cancer." (PMID 36139452, 2022). "Although PNPLA3 and TM6SF2 appear to be the most prominent hepatic steatosis determinants across the population, additional genetic deficiencies, which have been relatively infrequent or less significant, have been shown to produce fatty liver metabolism." (PMID 36557278, 2022). "We conducted this study to explore the association between genetic variations in TM6SF2 rs58542926, PCSK9 rs505151 and PCSK7 rs2277287 and hepatic steatosis in liver transplant recipients." (PMID 34876018, 2021). "When fed a normal diet, the Tm6sf2 knockout mice developed hepatic steatosis, elevated liver enzymes and hypocholesterolaemia, recapitulating the human phenotype." (PMID 33544287, 2021).
Hepatic steatosis (continued). "Transmembrane 6 superfamily member 2 (TM6SF2) is involved in VLDL secretion, and a loss of function due to a single nucleotide polymorphism (rs58542926) has been linked to liver steatosis, inflammation and fibrosis." (PMID 31010049, 2019). "Five fatty liver disease-associated SNPs (rs780094 (GCKR), rs2281135 (PNPLA3), rs8418 (PNPLA3), rs58542926 (TM6SF2), rs2980875 (TRIB1)) passed the significance threshold of <0.05 and were directionally consistent with previous studies." (PMID 30978214, 2019). "We also found that variants in TRIB1, TM6SF2 and APOE had stronger effects on NAFLD compared with cirrhosis, indicating that they may primarily exert their effect on cirrhosis via fatty liver disease." (PMID 38632349, 2024). "TM6SF2 is localized in the endoplasmic reticulum (ER) and ER-Golgi intermediate region and plays a key role in intracellular lipidization of very low density lipoproteins, thereby preventing fatty liver disease." (PMID 37753315, 2023). "The severity of hepatic steatosis is modulated by genetic variants, such as patatin-like phospholipase domain containing 3 (PNPLA3) rs738409, transmembrane 6 superfamily member 2 (TM6SF2) rs58542926, and membrane-bound O-acyltransferase domain containing 7 (MBOAT7) rs641738." (PMID 36555467, 2022). "Genetic variations in TM6SF2 rs58542926 and PCSK9 rs505151 might be associated with hepatic steatosis in liver transplant recipients." (PMID 34876018, 2021). "TM6SF2 (rs58542926 c.499C > T) and PNPLA3 (rs738409 c.444C > G) polymorphisms were evaluated regarding their association with clinical and laboratory data, histological liver steatosis and fibrosis, and with components of the metabolic syndrome." (PMID 33622266, 2021). "While data from multiple human studies have established the strong association of TM6SF2 E167K mutant variant with NAFLD, the exact mechanism how the loss of TM6SF2 function causes hepatic steatosis is not entirely clear." (PMID 34575933, 2021). "Notably, EASL–EASD–EASO Clinical Practice Guidelines35 already suggest genotyping for TM6SF2 and PNPLA3 to select patients with higher risk of hepatic steatosis." (PMID 29487372, 2018). "Interestingly, adiposity augments the effects of PNPLA3 I148M and TM6SF2 E167K mutations on fatty liver disease without affecting other adiposity-related parameters, suggesting a diet–gene interaction." (PMID 38247511, 2024). "Given that deficiency of TM6SF2 impairs TG transportation from the liver to circulation, one might assume high-fat diet (HFD) challenge could increase hepatic lipid accumulation and aggravate hepatic steatosis." (PMID 32776921, 2020). "Moreover, genetic polymorphisms, such as Patatin-like phospholipase domain-containing protein 3 (PNPLA3), transmembrane 6 superfamily member 2 gene (TM6SF2) and membrane bound O-acyltransferase domain containing 7 gene (MBOAT7), are also associated with hepatic steatosis and fibrosis." (PMID 29874807, 2018). "The Tm6sf2−/− mice may provide an improved model for the progression of fatty liver disease." (PMID 27013658, 2016). "The factors included age, gender, BMI, T2DM, HT, DLP, AST, ALT, platelet count, liver steatosis grade, PNPLA3 rs738409, TM6SF2 rs58542926, and HSD17B13 rs6834314; as well as VCTE, M2BPGi, FIB-4, APRI, and NFS." (PMID 40002828, 2025). "Thus, use of this in vitro model along with high-throughput experimental study design such as high-content image analysis used in this study could be a valuable tool to perform further functional analysis on TM6SF2 or other GWAS identified genetic modifiers of hepatic steatosis." (PMID 34575933, 2021). "Major genetic determinants of hepatic steatosis in the population include PNPLA3 I148M, TM6SF2 E167K and GCKR P446L." (PMID 30355853, 2018). "However, other fatty liver associated genotypes such as TM6SF2 variants were not explored." (PMID 27843495, 2016).
Hepatic steatosis (continued). "Genetic variations (PNPLA3, TM6SF2, GCKR, MBOAT7, MERTK, and HSD17B13) are one of the non-modifiable risk factors for metabolic dysfunction-associated fatty liver disease (MAFLD) and MASLD." (PMID 40507973, 2025). "TM6SF2 is involved in the VLDL-TG secretion pathway (inactivation of TM6SF2, a gene defective in fatty liver disease, impairs lipidation but not secretion of VLDL)." (PMID 36353245, 2022). "Genetic factors, including patatin-like phospholipase domain-containing protein 3 (PNPLA3) and transmembrane 6 superfamily member 2 (TM6SF2) affect liver steatosis with or without dyslipidemia." (PMID 30576386, 2018). "Furthermore, a study evaluating the combined effect of PNPLA3 and TM6SF2 polymorphisms in NAFLD found variants of PNPLA3 and TM6SF2 to be independently associated with hepatic steatosis, while PNPLA3 but not TM6SF2 was associated with liver fibrosis in a multivariable model." (PMID 34076851, 2021).
steatosis (48 papers, 2014 to 2025). Increased lipid within the cytoplasm of cells. "According to a meta-analysis, the minor allele T of TM6SF2 rs58542926 is associated with a higher risk of severe steatosis and fibrosis in children and adults." (PMID 40725464, 2025). "Variants in PNPLA3, GCKR, MBOAT7, and TM6SF2 were variably associated with liver injury and steatosis markers, with cohort-specific effects." (PMID 40943344, 2025). "The transmembrane 6 superfamily member 2 (TM6SF2) rs58542926-A allele has been proposed as another genetic risk factor associated with more severe steatosis, necro-inflammation, and advanced fibrosis." (PMID 38999436, 2024). "In particular, the rs738409 SNP of PNPLA3 (I148M) and the rs58542926 SNP of TM6SF2 (E167K) are independent risk factors for liver steatosis and steatosis severity in patients with HCV infections." (PMID 37400794, 2023). "The donor TM6SF2 (transmembrane 6 superfamily member 2) c.499A allele is an independent risk factor of liver graft steatosis following LT in addition to the effects of donor PNPLA3 c.444G allele." (PMID 35096933, 2021). "It is not a surprise, therefore, that these are variants in genes—like PNPLA3 and TM6SF2—where the minor alleles alter protein function and promote steatosis, associated with both qualitative and quantitative alterations in hepatic fat content." (PMID 33808740, 2021). "TM6SF2 rs58542926 was identified as a modifier of hepatic fibrogenesis and was associated with histological severity of steatosis, increased hepatic inflammation and fibrosis." (PMID 30875804, 2019). "Polymorphisms in genes that modulate lipid deposition in hepatocytes such as patatin-like phospholipase domain-containing protein 3 (PNPLA3) and transmembrane six superfamily member 2 (TM6SF2) predispose people to steatosis." (PMID 28883965, 2016). "Here, carriage of each copy of the TM6SF2 rs58542926 C>T minor allele was associated with increased risk of greater steatosis (odds ratio (OR) 1.379, 95%CI 1.019–1.865; P=0.037), although with a marginal level of significance." (PMID 24978903, 2014). "Indeed, PNPLA3 was associated with a higher risk for both steatosis and hepatic fibrosis, while TM6SF2 was primarily linked with steatosis and MBOAT7 with hepatic fibrosis." (PMID 38809396, 2024). "Altogether, PNPLA3 p.I148M and TM6SF2 p.E167K variants may promote steatosis and steatohepatitis which may indirectly predispose to progression of liver scarring (fibrosis and cirrhosis)." (PMID 36028802, 2022). "Finally, Tm6sf2 liver-specific knockout mice are more susceptible to HCC since they display increased steatosis, greater tumor burden, and increased tumor area compared to non-transgenic floxed control mice when tumorigenesis is chemically/dietary induced." (PMID 36555433, 2022). "For example, the single nucleotide polymorphisms (SNPs) in phospholipase domain-containing 3 (PNPLA3) and transmembrane 6 superfamily member 2 (TM6SF2) gene have been recently associated with the development of steatosis, NAFLD-related hepatocellular carcinoma (HCC), and the stage of liver fibrosis." (PMID 34746177, 2021). "Moreover, the variant showed an additive effect with PNPLA3 and Transmembrane 6 Superfamily Member 2 (TM6SF2) SNPs in determining the risk for steatosis." (PMID 28629152, 2017). "Genetic variations in Patatin-like phospholipase domain-containing protein 3 (PNPLA3), transmembrane 6 superfamily 2 (TM6SF2) or other genes associated with steatosis could possibly explain the association between lean NAFLD and the increased risk of future development of severe liver disease." (PMID 38405152, 2024). "In vitro studies revealed that TM6SF2 siRNA inhibition was associated with the reduced secretion of very-low density lipoproteins (VLDLs) and increased cellular TG concentrations and lipid droplet levels, whereas TM6SF2 overexpression reduced liver cell steatosis." (PMID 37445895, 2023).